NRP1 (neuropilin 1)
Diseases named in the same sentence as NRP1 in open-access papers (continued):
Sharing a sentence is not in itself a finding about the gene and the disease.
gastric cancer (continued). "The detection of NRP1 protein expression might be useful to determine the lymph node metastasis in patients with gastric cancer." (PMID 33014187, 2020). "Gastric cancer cells also produce neutrophilin-1 (NRP-1) and interleukin 1-α." (PMID 33167519, 2020). "We used prediction tools to detect miRNAs that may simultaneously regulate VEGFR1/2 and NRP1, and we finally determined that miR-590 can simultaneously regulate VEGFR1/2 and NRP1 in gastric cancer." (PMID 32303680, 2020). "Published data have shown that the analysis of NRP1 expression levels could provide a predictive marker of clinical outcome and prognosis in gastric cancer." (PMID 33014187, 2020). "In gastric cancer, NRP1 expression confers cancer stemness with binding to Lin28B." (PMID 32408477, 2020). "However, the value of NRP1 expression in the tumor immune microenvironment in stomach cancer remains to be studied although NRP1 is regarded as an immune-related gene and its expression is negatively correlated with patient OS." (PMID 32408477, 2020). "Additionally, expression of NRP1 protein is significantly up-regulated in gastric cancer tissues and cell lines." (PMID 32412912, 2020). "The present results indicate that NRP-1 may be a potentially valuable biomarker and therapeutic target for gastric cancer." (PMID 26795388, 2016). "Gastric cancer tissues expressed higher levels of NRP-1 compared to normal gastric mucosa." (PMID 26795388, 2016). "Taken together, the present results suggest that NRP-1 may be a valuable biomarker and potential therapeutic target for gastric cancer, particularly for those expressing higher levels of NRP-1." (PMID 26795388, 2016). "Human gastric cancer cells expressed different levels of NRP-1 protein, and mRNA." (PMID 26795388, 2016). "Because NRP1 is a downstream target of miR-338, we assumed that miR-338 could determine the epithelial phenotype of gastric cancer." (PMID 24736504, 2014). "Thus, we conclude that miR-338 acts as a potential tumor suppressor in gastric cancer, a function that is accomplished by curbing the expression of NRP1." (PMID 24736504, 2014). "Thus, we conclude that miR-338 inhibits gastric cancer cell migration, invasion and proliferation, as well as promoting apoptosis, by decreasing the expression of NRP1, which increases ERK, Akt and P38MAPK signaling." (PMID 24736504, 2014). "We speculate that NRP1 expression was already upregulated in gastric cancer, so further overexpressed NRP1 cannot significantly increase tumor vasculature but can restore tumor vasculature which has been reduced by miR-338." (PMID 24736504, 2014). "Altogether, these results demonstrated that miR-338 could inhibit EMT via NRP1 in gastric cancer cells." (PMID 24736504, 2014). "The goal of this study was to identify miRNAs that could inhibit the growth, invasion and metastasis of gastric cancer by targeting NRP1 expression." (PMID 24736504, 2014). "But why reduced NRP1 in gastric cancer cells can curb the D-MVA of xenografted tumor?" (PMID 24736504, 2014). "Moreover, we found that miR-338 inhibited gastric cancer cell migration, invasion, proliferation and promoted apoptosis by targeting NRP1 expression." (PMID 24736504, 2014). "The result shows that NRP1 can drive EMT process in gastric cancer." (PMID 24736504, 2014). "We hypothesized that EGF, as a regulator of other angiogenic factors such as VEGF in other tumour types, regulates both VEGF and NRP-1 in human gastric cancer cell lines." (PMID 12618892, 2003). "Five of seven gastric cancer cell lines constitutively expressed NRP-1 mRNA." (PMID 12618892, 2003). "In our study, five of seven gastric cancer cell lines expressed NRP-1 mRNA." (PMID 12618892, 2003). "In gastric cancer (GC), high expression of NRP1 is closely related to the development of tumor progression and associated with poor overall survival." (PMID 33014187, 2020).
gastric cancer (continued). "Furthermore, recent report indicated that anti-NRP-1 mAb might be a novel therapeutic approach in the treatment of gastric cancer." (PMID 33014187, 2020). "However, whether VEGFR1/2 and NRP1 are regulated by the same upstream mechanism is unclear, especially in gastric cancer." (PMID 32303680, 2020). "Therefore, we investigated whether depletion of NRP-1 could suppress the activation of these pathways stimulated by respective ligands in gastric cancer cells." (PMID 26795388, 2016). "miR-338 may therefore regulate gastric cancer cell EMT via NRP1." (PMID 24736504, 2014). "Studies on breast and gastric cancer have shown that RNA binding proteins such as PUM2 and Lin28B can bind to NRP1 mRNA, increasing its stability and expression, thereby affecting protein levels." (PMID 40806445, 2025). "There is a relationship between CNN1 and tumor-infiltrating lymphocytes (TILs), and the marker genes NRP1 and TNFRSF14 of TILs are significantly related to CNN1 expression in gastric cancers." (PMID 37153789, 2023). "Specifically, 8 genes (NRP1, MNX1AS1, SSRP1, PRDX2, PLRG1, LGALS4, SNX5 and FXYD3) were found to be highly expressed in stomach cancer tissues compared to normal tissues." (PMID 35831348, 2022). "Specifically, 8 genes NRP1, MNX1, SSRP1, PRDX2, PLRG1, LGALS4, SNX5 and FXYD3) which are highly expressed in stomach cancer were significantly down-regulated in PRU treated samples." (PMID 35831348, 2022). "Validation of the RIPK genes through GEPIA identified 8 genes (NRP1, MNX1, SSRP1, PRDX2, PLRG1, LGALS4, SNX5 and FXYD3) which are highly expressed in stomach cancer were significantly down-regulated in PRU treated samples." (PMID 35831348, 2022). "GRg3 downregulates NRP1 expression, blocks the interaction between NRP1 and FN1, and inhibits the malignant progression of gastric cancer MGC-803/MKN-28." (PMID 36313365, 2022). "NRP1 is a prognostic marker, hypomethylated and co-expressed with PDGFRB resulting in reduced gastric cancer survival." (PMID 33521362, 2021). "We aimed to determine whether Neuropilin-1 (NRP1) promotes gastric cancer (GC) metastasis by inducing epithelial-mesenchymal transition (EMT), and to clarify its regulatory mechanism." (PMID 33995640, 2021). "And CSF1R of CD8 + Tcell, CCL2, VSIG4 of M2 Macrophage, NRP1 of Th1, TGFB1 of Treg cell presented strong correction with PCOLCE expression in gastric cancer (P < 0.001; Cor value ≥ 0.40)." (PMID 33392251, 2020). "CSF1R of CD8 + Tcell, CCL2, VSIG4 of TAM, NRP1, TGFB1 of Th1 cell presented significantly correlate with PCOLCE expression in gastric cancer (P < 0.001; Cor value ≥ 0.40)." (PMID 33392251, 2020). "As a transcription factor, SNAIL inhibits the expression of miR-590, thereby upregulating the expression levels of NRP1 and VEGFR1/2; this leads to the development of EMT in gastric cancer and the upregulation of SNAIL." (PMID 32303680, 2020). "NRP1 activates tumor angiogenesis through interaction with VEGF and its receptor and promotes the growth and metastasis of gastric cancer." (PMID 32408477, 2020). "In the study for testing the therapeutic effects, we established subcutaneous tumors by using another gastric cancer cell line, BGC823, which was also shown to express higher levels of NRP-1." (PMID 26795388, 2016). "We found that gastric cancer cell migration, invasion, proliferation and apoptosis were restored in the AGS cell line with forced miR-338 expression and NRP1 restoration." (PMID 24736504, 2014). "miR-338 can decrease migratory, invasive, proliferative and apoptotic behaviors, as well as gastric cancer EMT, by attenuating the expression of NRP1." (PMID 24736504, 2014). "To analyse the regulation of NRP-1 expression by EGF, we studied NCI-N87 and ST-2 human gastric cancer cells, which expressed relatively high levels of EGF-R." (PMID 12618892, 2003). "We examined the expression of NRP-1 mRNA and EGF-R protein in seven human gastric cancer cell lines." (PMID 12618892, 2003).
gastric cancer (continued). "In this study, we examined NRP-1 and EGF-R expression in human gastric cancer cell lines and evaluated the effect of EGF on NRP-1 and VEGF expression." (PMID 12618892, 2003). "The expression of NRP-1 mRNA and EGF-R protein by human gastric cancer cell lines was examined by RT–PCR and Western blot analysis, respectively." (PMID 12618892, 2003). "In summary, we have shown that EGF and EGF-R play a role in the regulation of NRP-1 and VEGF expression via multiple signalling pathways in human gastric cancer cells." (PMID 12618892, 2003). "In the present study, we examined the expression of NRP-1 and EGF-R and the effect of EGF on NRP-1 and VEGF expression in human gastric cancer cells." (PMID 12618892, 2003). "Furthermore, NRP-1 was shown to directly interact with fibronectin-1 (FN1), which promotes epithelial-mesenchymal transition (EMT) in gastric cancer cells." (PMID 40430075, 2025). "Finally, we carried out qRT-PCR analysis of the expression levels of RGS2, GNAI2, ANXA5, MARCKS, CD36, NRP1, and PDE4A in gastric cancer cells." (PMID 38274323, 2024). "Then, we detected the NRP1 expression in GES-1 cell line and gastric cancer cell lines." (PMID 35164743, 2022). "In addition, the overexpression of miR-590 inhibits the migration, invasion, proliferation and D-MVA levels of gastric cancer cells in vivo and in vitro by targeting VEGFR1/2 and NRP1." (PMID 32303680, 2020). "The expression of NRP1 protein in gastric cancer was not related to gender, age, and Laurèn's classification." (PMID 33014187, 2020). "The level of NRP-1 expression was significantly correlated with clinical staging, tumor differentiation and pathological types of gastric cancer, but not with patients’ gender and age." (PMID 26795388, 2016). "NRP-1 depletion counteracted the activation of VEGF/VEGFR2, EGF/EGFR and HGF/c-Met pathways stimulated by respective ligands, indicating that NRP-1 acts as multifunctional co-receptors in gastric cancer cells." (PMID 26795388, 2016). "NRP-1 is shown to participate as co-receptors in the activation of the VEGF/VEGFR2, EGF/EGFR and HGF/c-Met pathways, which play key roles in the proliferation and metastasis of gastric cancer cells." (PMID 26795388, 2016). "Also, in a recently published biomarker evaluation study from the AVAGAST randomized trial in advanced gastric cancer, plasma VEGF-A and neuropilin-1 emerged as potential predictors of bevacizumab response." (PMID 23146280, 2012). "Activation of EGF-R might contribute to gastric cancer angiogenesis by a mechanism that involves upregulation of VEGF and NRP-1 expression via multiple signalling pathways." (PMID 12618892, 2003). "A recent study has shown that EGF induces NRP-1 mRNA expression in astrocytoma, but the expression and regulation of NRP-1 in gastric cancer has not previously been investigated." (PMID 12618892, 2003). "However, in preclinical models, similar results also demonstrated that NRP1 removal led to higher cell proliferation and lower cell migration, invasion, epithelial-to-mesenchymal transition (EMT) and angiogenesis in cervical cancer, NSCLC and gastric cancer." (PMID 35884516, 2022). "Finally, we found that the imbalance of 11 immune regulatory factors could predict the overall survival time of gastric cancer, including EZH2, NRP1, CD59, OsBPL1aBCL11B, BASP1, HNMT, CXCR4, ASGR2, ANXA5, CDH2." (PMID 34322132, 2021). "However, the role of NRP-1 in the progression of gastric cancer and the related mechanisms has not been fully elucidated." (PMID 26795388, 2016). "In addition, NRP1 is involved in the PI3K-Akt and EMT signaling pathways, which is highly reminiscent of previous research showing that NRP1 can induce EMT to enhance the migration and invasion ability of gastric cancer cells by activating the PI3K/Akt signaling pathway." (PMID 37190154, 2023).
lung carcinoma (65 papers, 2010 to 2025). "NRP1 is closely associated with the occurrence, progression and even metastasis of various tumors, such as bladder, colorectal, breast, and lung cancers." (PMID 37768204, 2023). "We next analyzed the chromatin status at the NRP1 target locus in lung cancer cells and found that NRP1-enriched regions were frequently associated with an active histone mark (H3K4me3)." (PMID 35993027, 2022). "LKB1 has been identified in lung cancer A549 cell lines as a RAB7 effector that alters NRP-1 trafficking causing NRP-1 localization to lysosomes and subsequent NRP-1 degradation." (PMID 31374919, 2019). "Inhibition of NRP1 expression by shRNA in both pancreatic and lung cancer cells containing dominant active KRASmt caused increased cell viability and tumor growth." (PMID 29018205, 2017). "These agents caused specific knockdown of SLUG and NRP1 genes resulting in the suppression of angiogenesis and growth of lung cancer." (PMID 26863567, 2016). "Both MAP2K4 and NRP1 are well known to be associated with lung cancer." (PMID 24669769, 2014). "In conclusion, PLN-5 is a potent dual-target inhibitor of PLK1 and NRP1 and is expected to be further developed for the treatment of lung cancer." (PMID 40820676, 2025). "Considering that PLK1 and NRP1 are essential for lung cancer development, targeting PLK1 and NRP1 simultaneously represents a potential therapeutic approach for lung cancer." (PMID 40820676, 2025). "Overexpression of PLK1 and NRP1 correlate with enhanced proliferative activity in lung cancer cells, thus the development of dual-target PLK1/NRP1 inhibitors holds great therapeutic promise." (PMID 40820676, 2025). "On the other hand, LINC00887 promoted lung carcinoma progression and metastasis by sponging miR-206 to regulate NRP1 expression." (PMID 38338866, 2024). "NRP1, involved in the VEGF/PI3K/Akt signalling pathway, is known for promoting cell migration, invasion and angiogenesis in lung cancer, while SLUG is implicated in facilitating invasion, migration and epithelial–mesenchymal transition of cancer cells." (PMID 39304978, 2024). "Systemic administration of an antibody that blocks VEGF binding to the b domain of NRP1 (anti-NRP1B) slows tumor growth in NRP1-expressing lung carcinoma." (PMID 37894289, 2023). "The NRP1 inhibitor EG00229 sensitizes A549 lung carcinoma cells to the cytotoxic chemotherapeutics paclitaxel and 5-FU." (PMID 37894289, 2023). "GATA3, an upstream transcriptional regulator of NRP1 gene, regulates the radioresistance of A549 and H1299 cells by opposite mechanisms, which provides a new target for radiotherapy of lung cancer." (PMID 35993027, 2022). "The results showed that GATA3 and NRP1, a key gene closely related to the high invasion and metastasis of lung cancer, were highly expressed." (PMID 35993027, 2022). "HIF-1α plays an important role in the development of VM in lung cancer by upregulating NRP1, indicating the potential therapeutic value of targeting NRP1 for the suppression of NSCLC metastasis and progression." (PMID 33850110, 2021). "Both are decreased in human lung cancer tissues, consistent with the increased methylation in promoter area and increased microRNAs that target NRP1 or TMPRSS2 in lung cancer tissues." (PMID 34168096, 2021). "It is possible that targeting of NRP1 to combat SARS-CoV-2 infection in lung cancer and asthma patients will reduce or prevent the severe form of infection." (PMID 34961486, 2021). "NRP1 expression down-regulation in experimental model of lung cancer reduces cell migration, invasion, and metastasis." (PMID 32766254, 2020). "Additional studies on changes in migration ability of lung cancer cells under different migration microenvironments have found that the migration ability of cells is closely related to NRP1 expression in the migration microenvironment." (PMID 31417646, 2019). "For instance, high expression of Nrp-1 observed in lung cancer correlates with invasive capacity and short disease-free survival." (PMID 31350404, 2019).
lung carcinoma (continued). "We found that NRP1 decreased lung cancer cell apoptosis and death in mouse tumor-bearing model after the action of ionizing radiation and that the effect was similar when compared to in vitro." (PMID 31417646, 2019). "Material and Methods: In this study, A549 lung cancer cell lines with different NRP1 expression levels were constructed in vitro, a two-dimensional (2D), three-dimensional (3D) co-culture system and tumor-bearing model was established in SCID mice." (PMID 31417646, 2019). "Western blot, qRT-PCR, immunofluorescence, cytometric bead array and flow cytometry were used to investigate the effect of the tumor microenvironment in NRP1-induced lung cancer cell radiation resistance." (PMID 31417646, 2019). "Our results showed that NRP1 has different effects in pancreatic and lung cancers depending on their KRAS genotype." (PMID 29018205, 2017). "NRP-1 has been shown to participate in the proliferation of cells from hepatocellular carcinoma, lung cancer, leukemia and lymphoma and medulloblastoma." (PMID 26795388, 2016). "The purpose of this study was to evaluate NRP-1 expression and metastatic properties in 94 endometrial cancer and matching serum specimens and in a lung cancer cell line." (PMID 26701889, 2016). "In the highly metastatic lung cancer cell line (H1792), stable LKB1 depletion caused increased migration in vitro and accentuated NRP-1 and NEDD9 expression in vivo." (PMID 26701889, 2016). "In lung cancer cells, the application of NRP1 specific inhibitory peptide (DG2) decreased the p-VEGFR2 expression levels." (PMID 26509169, 2015). "The NRP1 antagonist EG3287 was first tested for its ability to compete VEGF binding to NRP1-expressing lung carcinoma A549 cells." (PMID 20087344, 2010). "In the present study, we have shown that the NRP1 antagonist EG3287 significantly inhibited the migration of NRP1-positive lung carcinoma A549 cells in response to VEGF and serum." (PMID 20087344, 2010). "Given the pivotal role of PLK1 and NRP1 in promoting lung cancer proliferation, dual inhibition of PLK1 and NRP1 may serve as a potential therapeutic strategy for lung cancer." (PMID 40820676, 2025). "Furthermore, a D-peptide that targets NRP1, a cell–surface receptor overexpressed in lung cancer, and KRASG12D, a common oncogene, was developed using structure-based virtual screening." (PMID 40243822, 2025). "Lung cancer cells expressing NRP1 show increased levels of stemness markers and tumor-initiating properties, suggesting that NRP1 may be a feature of cancer stem cells (CSCs)." (PMID 37894289, 2023). "Importantly, CD also downregulated the expression of NRP1 from lymphocytes in mice and downregulated the expression of A2AR from the lung cancer cell line H1975 when treated with CD, implying the NRP1 mechanism probably through immuno-response pathways." (PMID 38138098, 2023). "Notably, some of the nine differential proteins (3HAO, ASAH1, CHMP5, FPRP, IBP3, MERTK, MUC18, NRP1, and PRIO) in tumor-forming rats have already been reported to be associated with lung cancer biomarkers/pathology/mechanisms or ovarian cancer metastasis." (PMID 32678190, 2020). "Importantly, our results also showed that TCR-mediated killing of autologous human lung cancer cells was inhibited in the presence of Sema-3A, highlighting a possible inhibitory role of the Nrp-1/Sema-3A axis in CTL functions." (PMID 31350404, 2019). "This indicates that in the process of radiation-induced lung cancer resistance induced by NRP1, both inflammatory reactions and the radiosensitivity of lung cancer cells may be reduced by regulating IL-6 and IL-8 in the tumor inflammatory microenvironment." (PMID 31417646, 2019). "The effects of intercellular interactions, and interactions of cells and extracellular matrix were explored to determine the impact of NRP1 on the inflammatory and migratory microenvironment of lung cancer cells and to elucidate its mechanism of action in radiation resistance." (PMID 31417646, 2019).